RNU6-811P (RNA, U6 small nuclear 811, pseudogene)
Gene: Small nuclear RNA gene on chromosome 10 (37,135,237 to 37,135,343, forward strand). Ensembl gene ENSG00000206796.
Homologues: Orthologues: chimpanzee U6 (100% identical), macaque U6 (96% identical), dog U6 (70% identical), rabbit U6 (70% identical), pig U6 (67% identical), rabbit U6 (65% identical). Paralogues in human: RNU6-1207P (96% identical), RNU6-1293P (93% identical), RNU6-156P (93% identical), RNU6-1210P (92% identical), RNU6-458P (92% identical), U6 (92% identical), RNU6-1132P (91% identical), RNU6-614P (91% identical), RNU6-452P (90% identical), RNU6-721P (90% identical), U6 (90% identical), RNU6-666P (89% identical), and 1288 more.